VIM (vimentin)
Diseases named in the same sentence as VIM in open-access papers (continued):
Sharing a sentence is not in itself a finding about the gene and the disease.
infection (continued). "Together, these two studies showed that vimentin, a constituent of intermediate filament (IF), undergoes changes upon infection and accompanies the MTs in the infected cell." (PMID 39769222, 2024). "We observed a higher aggregation of both vimentin and E-cadherin than those of the mock infection and TGF-β1 treatment." (PMID 37338373, 2023). "As expected, the expression of α-Sma, Col1α1, and Vimentin were significantly upregulated 30-, 60-, 90-day post infection compared with the uninfected group." (PMID 37490505, 2023). "Here, the authors characterise the role of the Salmonella effector SopB on the vimentin network and its contribution to infection." (PMID 36717589, 2023). "Our results reflected that CHIKV infection led to vimentin remodeling and formation of cage-like structures, which became more pronounced as the infection time increased." (PMID 37928675, 2023). "SS2 infection significantly increased vimentin expression at the membrane of STEC compared to the uninfected control." (PMID 36717839, 2023). "It was also shown that in certain conditions, including infection, immune cells such as monocytes or macrophages can express vimentin at the membrane or even secrete vimentin, suggesting a role during the immune response." (PMID 37475865, 2023). "Research has shown that the rearrangement and reorganization of vimentin intermediate filaments were induced by CHIKV-infection, which was consistent with our findings." (PMID 37928675, 2023). "In neutrophils, CDK5 can regulate the secretion of cytokines during infection or injury by phosphorylating vimentin." (PMID 37332205, 2023). "Upon CHIKV infection, vimentin started to lose its usual filamentous structures and retracted from the plasma membrane, which became more obvious as the infection time increased in “DMSO” group." (PMID 37928675, 2023). "Taken together, these results indicate that vimentin plays an important role in later infection processes following NDV attachment." (PMID 37848995, 2023). "Multiple studies have already shown that in the pathogen infection process, vimentin can play an essential role both intracellularly and extracellularly." (PMID 36912679, 2023). "Nevertheless, our results demonstrated that the C-terminal phosphatase activity of SopB is dispensable for vimentin rearrangement, by infection of SopBC460S expressed ΔsopB S. Tm." (PMID 36717589, 2023). "In this review, we will highlight the different roles that vimentin can play during pathogen infection of the host cell." (PMID 37475865, 2023). "Consistent with the murine infection model results, vimentin in STEC contributed to the transcription of IL-6, TNF-α, and IL-8." (PMID 36717839, 2023). "In agreement with vimentin reorganization, Cdc42 became enriched around SCVs post wild-type S. Tm infection, whereas it showed diffused distribution in un-infected or ΔsopB S. Tm infected condition." (PMID 36717589, 2023). "In contrast, wild-type RSV (RSV-WT) (multiplicity of infection [MOI] = 0.1) induced substantially lower vimentin expression than TGF-β1." (PMID 37338373, 2023). "Some of these miRNAs, such as miR-9 and miR-221/222 cluster, have been reported to promote EMT, a feature that infected BCPAP cells acquire after infection, as suggested by the upregulation of the mesenchymal marker vimentin." (PMID 37896899, 2023). "Vimentin intermediate filaments affect infection, virulence, and replication of viruses in the host cells." (PMID 35573702, 2022). "The results showed that the transcription and expression levels of vimentin increased significantly in DF-1 cells 6–72 h after infection with sporozoites." (PMID 34983604, 2022). "Vimentin has been shown to play important roles during infection by viruses from multiple families with different types of genomes (DNA, single-stranded RNA and double-stranded RNA) and replication cycles." (PMID 35683351, 2022).
infection (continued). "In the process of infection with human immunodeficiency virus, severe acute respiratory syndrome coronavirus, and other viruses, vimentin often acts as a co-receptor, enabling them to achieve effective invasion of cells." (PMID 35769479, 2022). "Vimentin on the cell surface is an attachment receptor that binds to VP1 via the N-terminus to enhance the infection." (PMID 36298746, 2022). "Host vimentin is a key protein in the process of infection of many pathogens, but its role differs among different pathogens, and its role in Eimeria infection has not been explored." (PMID 34983604, 2022). "Establishing the full range of the involvement of VIM in viral entry and infection will require further investigations." (PMID 35078919, 2022). "The presence of vimentin-positive cells and Iba-1-positive cells during the inflammatory process is a sign of activation of the immune response following first infection." (PMID 35336202, 2022). "In this work, we provide evidence that VIM plays an important functional role in cell entry and infection by SARS-CoV-2." (PMID 35078919, 2022). "To test this, we first transfected Neuro-2a cells with an IFN-β promoter luciferase reporter construct together with a plasmid expressing OTUD4 or VIM before infection at an MOI of 2 for 16 h." (PMID 35516420, 2022). "Knockdown of VIM significantly reduced infection of HUVEC-TERT cells compared to cells expressing control shRNA (P = 0.0089, two independent experiments, triplicates per group)." (PMID 35078919, 2022). "Conversely, when NS were incubated with heparin prior to infection, the vimentin web was still maintained even in infected cells." (PMID 36121298, 2022). "To confirm that VIM inhibited IB formation, we used a live cell-imaging system to observe the process of VIM regulating IB fusion under HPIV3 infection." (PMID 36108090, 2022). "The VP1 protein activates calmodulin dependent protein kinase II, which phosphorylates the N-terminal region of vimentin on serine 82 during infection." (PMID 36298746, 2022). "This suggests a reorganization of the microtubule network by the infection as also shown by staining of actin and vimentin filaments of the cytoskeleton (respectively)." (PMID 36223391, 2022). "The instrumental role of surface vimentin in the host cell invasion has also been demonstrated in infection by M. avium subsp." (PMID 35573702, 2022). "Total vimentin levels, phosphorylation, and solubility fluctuated at different time points after infection." (PMID 35433510, 2022). "In contrast, the VP1-A289T variant of EV-A71 weakened the binding capacity between VP1 and vimentin, and then reduced the infection towards the central nervous system." (PMID 36224635, 2022). "This study reveals for the first time that vimentin can inhibit the infection, replication, and release of DENV-2 in the brain tissue of suckling mice, and that it affects the viral load entering the circulation." (PMID 35433510, 2022). "At the cellular level, vimentin is involved in a variety of pathogen invasion and infection processes." (PMID 35433510, 2022). "In our study, morphological changes in DENV-2-infected HBMECs occurred within 1 h of infection, and vimentin went from being present throughout the cell to only being present around the nucleus." (PMID 35433510, 2022). "The results showed that after 24 h of infection, the vimentin accumulated around the sporozoites in DF-1 cells, which was similar to results found in other pathogens." (PMID 34983604, 2022). "The results showed that the phosphorylation level of host vimentin changed significantly after infection." (PMID 34983604, 2022). "Six days after infection, however, infected hiPSC-NS lost their integrity, and vimentin appeared dot-like resembling agglomeration." (PMID 36121298, 2022).
infection (continued). "RT-qPCR results showed that at 24 h post-infection, ASFV B646L gene (encoding ASFV P72 structural protein) expression gradually increased with increasing VIM or TRIM21 transfection dose, but gradually decreased with TUFM." (PMID 36406406, 2022). "Surprisingly, upon generating a vimentin‐null cell line, we found that infection was still sensitive to acrylamide and that viral replication was not altered by the loss of vimentin." (PMID 33792166, 2021). "Binding to surface expressed vimentin was also found to be critical for infection with the flaviviruses Japanese encephalitis virus (JEV) and dengue virus (DENV)." (PMID 34960740, 2021). "Taken together, vimentin staining and cell morphology/localisation suggest that after infection of PCLS with S. suis, COX-2 is most likely primarily produced in fibroblasts in the bronchiolar area." (PMID 33673302, 2021). "These enveloped positive-sense single-stranded RNA viruses showed reduced infection when pre-incubated with recombinant vimentin protein and/or fragments corresponding to its head and tail domains (JEV) or rod domain (DENV), respectively." (PMID 34960740, 2021). "For animals infected with the Erfurt strain, characterized by rapid mortality (100%, between 3- and 4-days post-infection), vimentin expression was mainly comparable to the uninfected controls, with elevated protein expression only at 60 h post-infection." (PMID 34372621, 2021). "Recent studies have also provided evidence that extracellular vimentin is involved in several diseases, in repair mechanisms for spinal cord injury, and in the infection mechanisms of viruses." (PMID 34299089, 2021). "Because vimentin is involved in the infection and replication of virus in cells, its decrease in expression affects the replication of virus." (PMID 34579242, 2021). "Meanwhile, the serum expression of vimentin depended on the duration of the infection and the strain used in the experiment." (PMID 34372621, 2021). "Although the exact mechanism of surface VIM/vi-VIM induction needs to be elucidated, infection with rather diverse viruses apparently changes the conformation of intracellular VIM thereby allowing its presentation on the cell surface." (PMID 34571970, 2021). "Meanwhile, during the Rossi strain infection, increased vimentin expression was indicated in 12 h (p = 0.001), 24 h (p = 0.0001), 36 h (p = 0.0003), 52 h (p = 0.04), and 56 h (p = 0.001) post-infection in comparison to the healthy controls." (PMID 34372621, 2021). "Targeting the increased vimentin expression on liver cells by hzVSF after infection with HBV or woodchuck hepatitis virus (WHV) was demonstrated initially." (PMID 34571970, 2021). "Surprisingly, vimentin overexpression in multiple cell lines resulted in decreased levels of infection, while vimentin knockout by siRNA led to an increase in infection." (PMID 33672181, 2021). "During infection of monocytes with Mycobacterium tuberculosis, vimentin is exposed on the cell surface and acts as a ligand for NKp46 receptor on natural killer cells, inducing their activation and lysis of infected cells." (PMID 32630064, 2020). "Vimentin has been shown to play important roles during infection by viruses from multiple families with different types of genomes (DNA, single-stranded RNA, double-stranded RNA, etc.)and replication cycles." (PMID 32630064, 2020). "Specifically, vimentin’s rod domain has been shown to interact with the envelope protein of the virus in endothelial cells and promote virus absorption and subsequent infection." (PMID 32630064, 2020). "Brains of mice infected with either virus had an expansion of the vimentin+ region abutting the ventricles, indicating damage to and/or disruption of the ependymal lining as a result of infection." (PMID 32940605, 2020). "Vimentin has been shown to coimmunoprecipitate 2C of the foot-and-mouth disease virus, and together they organize replication sites for efficient infection." (PMID 31619557, 2020).
infection (continued). "Influenza A virus viral ribonucleoprotein was also shown to be bound by vimentin in the cytoplasm, thereby preventing it from entering the nucleus and rather downregulating the infection." (PMID 31619557, 2020). "At 24 h post-infection, vimentin recruitment to the CCV was visible, as judged by co-localization with LAMP2." (PMID 33282747, 2020). "A time course study showed that dsRNA and vimentin rearrangements both appeared around 3 to 4 h p.i. and became more pronounced during the progression of infection." (PMID 31619557, 2020). "In our earlier studies, we noticed that the morphology of the cellular vimentin network correlated with echovirus-1 (EV-1) infection efficiency in tested human cell lines." (PMID 31619557, 2020). "We show that infection by a member of the human EV group B viruses leads to massive rearrangements of the intermediate filament, vimentin." (PMID 31619557, 2020). "Nevertheless, the predominant cellular phenotype among each cell population seems to be dependent on the infection status, thus suggesting an indirect role of the virus in the intracellular redistribution of vimentin." (PMID 32627957, 2020). "Vimentin is secreted by activated macrophages, helping to combat infection by acting as a proinflammatory factor, triggering the generation of oxidative metabolites and bacterial killing." (PMID 32630064, 2020). "In contrast to infection with C. trachomatis and C. burnetii, the infection with A. phagocytophilum resulted in increased vimentin expression." (PMID 33282747, 2020). "Reducing the availability of surface vimentin, either with anti-vimentin antibodies, siRNA or chemical treatment to induce network disruption attenuated cellular infection." (PMID 32630064, 2020). "In this work, they also found that vimentin is reorganized during infection, which was critical for the formation of the replication complexes." (PMID 32630064, 2020). "Based on the results of our phosphoproteomic analysis, we found that the phosphorylation levels of host cell vimentin were significantly modulated by T. gondii at the two infection stages." (PMID 33363051, 2020). "Analysis of viral function revealed that the capacity of viral attachment, replication, and protein synthesis and secretion decreased in HBMECs during an EV-A71-289A infection, the infectivity being higher than that of EV-A71-289T upon VIM-KO." (PMID 31121933, 2019). "Modification of the host cell cytoskeleton by bacterial pathogens to facilitate infection is well characterised and interest in the role of vimentin in response to bacterial infection is now growing." (PMID 30699149, 2019). "Next, we assessed the effect of blocking the vimentin-GBS interaction by treating hCMEC with anti-vimentin antibodies prior to infection with GBS." (PMID 31181121, 2019). "We observed that vimentin protein was present throughout the cytoplasm of uninfected hCMEC, but during infection GBS co-localized with vimentin near the surface of infected cells." (PMID 31181121, 2019). "In vivo infection with N. brasiliensis significantly reduced vimentin expression within the female genital tract, confirming the relevance of these in vitro findings." (PMID 30069018, 2018). "Vimentin, a cellular cytoskeleton component, also plays an important role in the infection process of PRRSV as the anti-vimentin mAb has been shown to block PRRSV infection." (PMID 30053894, 2018). "The morphological change was further demonstrated by confocal, which showed the spindle-shaped distribution of vimentin after infection of SH0165 (108 CFU/mL) or TGF-β1 (10 ng/mL)." (PMID 30258822, 2018). "We thus investigated this and demonstrate that infection significantly reduced the expression of vimentin in the female genital tract, while resulting in a trend toward decreased expression of N-cadherin, when compared to that of naïve mice." (PMID 30069018, 2018).
infection (continued). "Whereas in our “protective” regimen, we have used the simultaneous administration of iPSC-Mac and P. aeruginosa, administration of iPSC-derived ViM prior the infection would provide additional insights in the protective properties." (PMID 30504915, 2018). "This work identifies InlF as a bacterial surface protein with specific relevance for infection of the brain and underscores the significance of host cell surface vimentin interactions in microbial pathogenesis." (PMID 29487235, 2018). "Chlamydia trachomatis requires OGT activity and vimentin glycosylation sites to maintain inclusion integrity during infection." (PMID 29513221, 2018). "Vimentin has been described as an important molecule during ASFV morphogenesis by changing its localization to viral factories after in vitro infection." (PMID 30208957, 2018). "In vivo infection experiments with vimentin knockout mice and infection of wild-type mice with ΔinlF mutant bacteria suggested that the presence of vimentin and expression of InlF by L. monocytogenes are necessary for maximal colonization of the brain in mice." (PMID 29487235, 2018). "Both preincubation of the viral particles with soluble recombinant vimentin protein and overexpression of vimentin on the cell surface led to a substantial decrease in viral uptake and infection." (PMID 28566373, 2017). "We preincubated the viral particles with soluble human recombinant vimentin protein before infection." (PMID 28566373, 2017). "The increased expression of α7 nAChR in mouse brain cortex with E. coli K1 E44 infection was also abolished by vimentin KO." (PMID 27657497, 2016). "During infection with retroviruses such as bovine leukemia virus (BLV) and HIV, the viral-encoded protease specifically cleaves vimentin." (PMID 27603133, 2016). "This suggests that the bacterium can subvert the vimentin network to modulate host immune signaling during infection." (PMID 27096872, 2016). "Withaferin A, which inhibits soluble vimentin, reduces vimentin recruitment to the ApV, optimal ApV formation, and the bacterial load when administered prior to infection but is ineffective once vimentin has assembled on the ApV." (PMID 29056733, 2016). "A vimentin cage was then subsequently formed around the virus assembly site during the later stages of infection." (PMID 26801988, 2016). "A recent study has reported a different outcome of M. tuberculosis infection: here vimentin is downregulated in M. tuberculosis-infected macrophages compared to infections with an avirulent M. tuberculosis strain." (PMID 27096872, 2016). "We propose that the superficial vimentin acts as a recruiting device that increases the infection of DENV to VECs." (PMID 27910934, 2016). "Once inside the cell, the bacterium also targets vimentin to the ApV to modulate extracellular signal-related kinases 1 and 2 (Erk1/2) signaling and promote infection." (PMID 29056733, 2016). "Rearrangement of cytosolic vimentin and formation of vimentin cages around the viral factories were observed during the infection of vaccinia virus and African swine fever virus." (PMID 26801988, 2016). "Studies on mammalian porcine reproductive and respiratory syndrome virus, Japanese encephalitis virus, and cowpea mosaic virus also provided evidence that binding of virus to surface vimentin can facilitate internalization and infection." (PMID 26801988, 2016). "For another intestinal pathogen, Salmonella enterica (serovar Typhimurium), it has been shown that the infection can remodel the vimentin network." (PMID 27096872, 2016). "Immunofluorescent staining also showed that miR-1 infection led to the upregulation of E-cadherin and the downregulation of vimentin and N-cadherin." (PMID 26036633, 2015). "Vimentin expression in the vimentin knockdown cell line (VK-U251) was compared to that of the normal U251 cells by Western blot analysis before infection with EV71." (PMID 24073199, 2013).